SNORD96A (small nucleolar RNA, C/D box 96A)
Synonyms: U96a
Gene: Small nucleolar RNA gene on chromosome 5 (181,241,814 to 181,241,892, reverse strand). Ensembl gene ENSG00000272296.
Gene Ontology:
Biological process: RNA processing
Cellular component: nucleolus
Homologues: Orthologues: chimpanzee SNORD96 (99% identical), macaque SNORD96 (96% identical), rabbit SNORD96 (96% identical), pig SNORD96 (91% identical), dog SNORD96 (90% identical), mouse Snord96a (85% identical), rat Snord96a (84% identical). Paralogues in human: SNORD96B (92% identical).
Diseases named in the same sentence as SNORD96A in open-access papers:
SNORD96A is named in the same sentence as 1 disease in open-access papers, as found by Europe PMC text mining. Sharing a sentence is not in itself a finding about the gene and the disease.
SNORD96A shares sentences with these, for which no sentence is quoted: osteoarthritis (1 paper).